EIF3C (eukaryotic translation initiation factor 3 subunit C)
Diseases named in the same sentence as EIF3C in open-access papers (continued):
Sharing a sentence is not in itself a finding about the gene and the disease.
prostate carcinoma (7 papers, 2022 to 2025). A carcinoma that arises from epithelial cells of the prostate gland. "In prostate cancer, CircPDE5A regulates EIF3C (a paralog of EIF3B) to suppress m6A methylation of EIF3C mRNA, indirectly influencing MAPK signaling." (PMID 40691141, 2025). "EIF3C promotes the proliferation, migration, and invasion of prostate cancer, pancreatic cancer, and lung adenocarcinoma." (PMID 37996918, 2023). "Several clinical studies reported the significance of EIF3C in predicting patients' prognosis in various human cancers, such as intrahepatic cholangiocarcinoma, prostate cancer, and endometrial cancer." (PMID 36157221, 2022). "However, the specific role of EIF3C in prostate cancer is still elusive." (PMID 35650605, 2022). "Emerging studies have reported that circPDE5A blocks the WTAP-dependent m6A methylation of eIF3c mRNA by forming a circPDE5A-WTAP complex, ultimately disrupting the translation of eIF3c for prostate cancer cell migration and invasion." (PMID 36360287, 2022). "Multiple components of the EIF3 are now known to be dysregulated in multiple cancers (EIF3A in breast, cervical, lung and gastric cancers; EIF3B in breast and gastric cancers; EIF3C in testicular cancers; and EIF3H in prostate cancers)." (PMID 35528200, 2022). "However, the role of EIF3C in prostate cancer has not been discussed." (PMID 35650605, 2022).
glioma (6 papers, 2018 to 2023). A benign or malignant brain and spinal cord tumor that arises from glial cells (astrocytes, oligodendrocytes, ependymal cells). "This study showed a significant increase in eIF3C staining in glioma samples compared to staining detected in brain tissues from traumatic brain injury patients used as control (n = 25)." (PMID 31795417, 2019). "Nevertheless, eIF3C together with other eIF3 subunits have been studied in glioma tissues, in vitro and in vivo by other research teams." (PMID 31795417, 2019). "eIF3c was found highly expressed in glioma samples compared to different non-cancer brain tissues, and eIF3c levels were associated with tumor grades." (PMID 36994107, 2023). "Finally, these authors showed that lower eIF3C expression reduces tumor growth in vivo using a glioma xenograft mouse model." (PMID 31795417, 2019). "eIF3C, eIF3D, eIF4E and 4E-BP1 correlated with tumour grade with significantly higher levels in HGG compared to LGG (low grade glioma)." (PMID 37907716, 2023). "More studies showed knockdown of EIF3B, decreasing EIF3C, and silencing EIF3D and EIF3E alleviated proliferation and migration of glioma cells." (PMID 32565801, 2020). "EIF3C also known as EIF3S8 or eIF3-p110 were found to be upregulated in neurofibromatosis type 2 (NF2), colon cancer, glioma, HCC and breast cancer." (PMID 29568350, 2018). "In addition, eIF3C (which expression data are lacking in REMBRANDT and TCGA as evoked above) was investigated by immunohistochemistry in glioma samples (n = 83)." (PMID 31795417, 2019).
melanoma (4 papers, 2020 to 2022). A malignant, usually aggressive tumor composed of atypical, neoplastic melanocytes. "In melanoma cells it has been demonstrated that in hypoxic conditions, EV exhibit a miRNome and proteome signature (AKR7A2, DDX39B, EIF3C, FARSA, PRMT5, VARS), which is associated with poor prognosis for the patients." (PMID 34439311, 2021). "Hypoxic melanoma EVs carried a hypoxic signature consisting of six proteins (AKR7A2, DDX39B, EIF3C, FARSA, PRMT5, VARS) which were significantly associated with a poor prognosis for melanoma patients." (PMID 32183388, 2020).
pancreatic cancer (4 papers, 2022 to 2023). "EIF3C was found to be upregulated in pancreatic cancer, and its knockdown significantly suppressed cell proliferation and enhanced cell apoptosis." (PMID 36157221, 2022). "EIF3C knockdown in HCT116 cells can significantly hamper cell proliferation and cause G2/M phase arrest, and its knockdown in pancreatic cancer cells could suppress cell proliferation and accelerate apoptosis." (PMID 36157221, 2022).
colon cancer (3 papers, 2016 to 2022). "Studies have found that the overexpression of EIF3C gene has a positive effect on colon cancer cell survival and progression which can be suppressed by lentivirus-mediated infection of EIF3C siRNA." (PMID 35814779, 2022). "Increased eIF3c transcript levels have been found in human testicular seminomas as well as increased eIF3c gene expression in colon cancer cells." (PMID 28083147, 2016). "Therefore, EIF3C silencing could be considered as a novel therapeutic tool for colon cancer treatment." (PMID 35814779, 2022).
endometrial cancer (2 papers, 2019 to 2022). Primary or metastatic malignant neoplasm involving the endometrium (mucous membrane that lines the endometrial cavity). "We further investigated the expression patterns of peIF2α, eIF2α, eIF3c, eIF3h, eIF4e, eIF4g, eIF5 and eIF6 in endometrial cancer compared to non-neoplastic patient samples using immunoblot analysis." (PMID 31817792, 2019).
head and neck carcinoma (2 papers, 2022 to 2023). A carcinoma that arises from the head and neck region. "The pathscan sandwich ELISA also preliminarily explored the protein expression signaling pathway associated with EIF3C affecting the apoptosis in pharyngeal squamous carcinoma cells, however, the specific regulatory mechanism of EIF3C in head and neck cancer remains to be further investigated." (PMID 36147539, 2022). "In this study, the role of EIF3C in head and neck cancer was investigated by constructing shRNA to down-regulate EIF3C expression." (PMID 36147539, 2022). "This study provides a theoretical basis for further understanding the molecular mechanism of EIF3C in the occurrence and development of head and neck cancer, and also provides a potential new target for the treatment of head and neck cancer." (PMID 36147539, 2022). "In order to clarify the biological function of EIF3C in head and neck cancer, this study constructed EIF3C-shRNA lentvirus and inhibited the expression of EIF3C to study the biological effects of EIF3C on the proliferation, growth and apoptosis of FaDu and 5-8F cells." (PMID 36147539, 2022). "In order to clear the eIF3C siRNA interference effect on eIF3C expression in head and neck carcinoma, eIF3C siRNA (siRNA-eIF3C) and the negative control siRNA (siRNA-NC) encapsulated in liposome were used to infect the human FaDu cell line and 5-8F cell line, both of which are from HNC." (PMID 38274829, 2023).
intrahepatic cholangiocarcinoma (2 papers, 2021 to 2022). A carcinoma that arises from the intrahepatic bile duct epithelium in any site of the intrahepatic biliary tree. "EIF3C is upregulated in renal cell carcinoma and intrahepatic cholangiocarcinoma." (PMID 36157221, 2022).
atherosclerosis (1 paper, 2022). A disease characterized by the build-up of fatty material and calcium deposition in the arterial wall resulting in partial or complete occlusion of the arterial lumen. "These processes are also involved in the pathology of atherosclerosis and could be promoted during this disease by upregulation of EIF3C." (PMID 35743538, 2022).
cervical cancer (1 paper, 2021). A primary or metastatic malignant neoplasm involving the cervix. "It is displayed in kaplan–Meier curves that higher expression level of EEF1D, CTU1, EIF3C, WDR43, NUFIP1, ZC3HAV1L and PRPF40B indicated a lower overall survival of cervical cancer patients." (PMID 34863153, 2021).
diabetes (1 paper, 2021). "We found 15 differentially-expressed genes among 20 RNA m6A methylation regulators, including EIF3C, FTO, METTL3, RBM15, etc; and 40 differentially-expressed genes among 46 diabetes related factors." (PMID 34084770, 2021).
lentivirus infection (1 paper, 2019). Virus diseases caused by the Lentivirus genus. "After shRNA lentivirus infection, the expression of EIF3C in the experimental group was inhibited." (PMID 31316002, 2019).
meningioma (1 paper, 2016). A generally slow growing tumor attached to the dura mater. "Additionally, in meningiomas, which have significantly reduced levels of schwannomin, eIF3c is upregulated, suggesting a role of eIF3c in tumor growth and proliferation." (PMID 28083147, 2016).
vitiligo (1 paper, 2025). Generalized well circumscribed patches of leukoderma that are generally distributed over symmetric body locations and is due to autoimmune destruction of melanocytes. "The authors concluded that KLB and EIF3C are key genes in OS regulation of AA and vitiligo and that KLB and EIF3C participate in disease progression by regulating T cells and neutrophils." (PMID 40943550, 2025).
tumor (26 papers, 2016 to 2025). "Nevertheless, similar to other tumor-specific proteins and associated PPIs, inhibiting eIF3C through direct protein-level regulation poses significant challenges." (PMID 38274829, 2023). "EIF3C (eukaryotic translation initiation factor 3 subunit C) is also upregulated during HCC tumor progression and is associated with poor patient survival." (PMID 35155236, 2022). "Higher expression of EIF3C in tumor samples is associated with poor patient survival in compared to that of lower expression HCC patients." (PMID 29568350, 2018). "Here, we showed that EIF3C (eukaryotic translation initiation factor 3 subunit C) is upregulated during HCC tumor progression and associated with poor patient survival." (PMID 29568350, 2018). "Similarly, studies have shown that eIF3C is also associated with cell growth, proliferation, and tumour invasion, and knockout eIF3C gene significantly inhibits these cellular properties." (PMID 34794452, 2021). "Nevertheless, the underlining molecular mechanisms for upregulated EIF3C to mediate tumor progression and serve as therapeutic target to improve patient survival remain unclear." (PMID 29568350, 2018). "Iacs-eif3c-RNA demonstrated the ability to overcome the pharmacological obstacle associated with targeting eIF3C, resulting in a significant reduction in eIF3C expression within tumor tissues, as well as effective tumor cell proliferating suppression and apoptosis promotion." (PMID 38274829, 2023). "Depletion of eIF3C resulted in reduced tumour cell proliferation, increased tumour cell apoptosis, and an increased shift to the G1-phase of the cell cycle when compared with control types." (PMID 38268823, 2024). "Meanwhile, this trend was also consistent with the inhibitory effect of Iacs-eif3c-RNA on tumor growth, which was likewise further supported by the results of H&E staining." (PMID 38274829, 2023). "In contrast to peptide and protein derived drugs that possess intricate structures and mechanisms, Iacs-eif3c-RNA exhibited a remarkable ability to suppress tumor growth in the HNC xenograft model by effectively downregulating the gene expression of eIF3C." (PMID 38274829, 2023). "siRNA has emerged as a highly promising modality for drug development targeting eIF3c, while its application is hindered by challenges pertaining to inadequate stability and insufficient concentration specifically within tumor sites." (PMID 38274829, 2023). "The excellent anti-tumor performance of Iacs-eif3c-RNA, as well as the important molecular biological function of eIF3C itself compelled us to explore its role in the treatment of chemotherapy-resistant HNC." (PMID 38274829, 2023). "Here, we constructed a HNC xenograft model using cisplatin (DDP)-insensitive FaDu cells to examine the anti-tumor ability of Iacs-eif3c-RNA." (PMID 38274829, 2023). "Tumor weights were significantly reduced in mice treated with Iacs-eif3c-RNA, supporting by the photographs of tumors and tumor-bearing mice." (PMID 38274829, 2023). "Immunohistochemical results indicated that the expression level of eIF3C in tumor tissues treated with Iacs-eif3c-RNA was significantly reduced, which proved that Iacs-eif3c-RNA enriched in tumor tissues and fully played the role of silencing target genes." (PMID 38274829, 2023). "Encouragingly, our findings suggested that Iacs-eif3c-RNA successfully suppressed the expression of the target gene eif3c in vivo, leading to the tumor growth inhibition." (PMID 38274829, 2023). "The results showed that down-regulating EIF3C inhibited the proliferation of FaDu and 5-8F cells, promoted their apoptosis, induced cycle arrest, and inhibited tumor growth in a mouse xenograft model." (PMID 36147539, 2022). "The results indicated that EIF3C knockdown reduced tumor growth as reflected by a decline in tumor volume and weight (all p < 0.01)." (PMID 36157221, 2022). "For instance, EIF3C can enhance hepatocellular carcinoma cell proliferation in vitro and tumor growth in vivo." (PMID 36157221, 2022).
tumor (continued). "eIF3C, eIF3D and eIF4E even correlated with tumor grade as their expression was significantly higher in HGG than in LGG." (PMID 33807050, 2021). "EIF3C is up-regulated in several cancers, and it is known that silencing EIF3C induces cell apoptosis and suppresses cell proliferation and tumor growth." (PMID 30897788, 2019). "We found that EIF3C mediated tumor progression via increasing release of oncogenic exosomes to potentiate angiogenesis and tumorigenesis in tumor microenvironment." (PMID 29568350, 2018). "We found that EIF3C is upregulated in HCC tumor samples in comparison with normal tissues in TCGA HCC dataset." (PMID 29568350, 2018). "Schwannomin is thought to employ its tumor suppressive functions by binding eIF3c and inhibiting eIF3c-mediated cell proliferation, possibly due to the role of eIF3c during protein translation initiation." (PMID 28083147, 2016). "As CD8+ T cells are known for their exceptional cytotoxic activity to tumor cells, overexpression of EIF3C in NPC patients might hinder anti-tumor immune response by potentially suppressing CD8+ T cells." (PMID 38400862, 2024). "To, sum up, these data indicated EIF3C as a tumor-promoting factor." (PMID 38400862, 2024). "The result showed that gold content in tumor increased with time, which indicated the Iacs-eif3c-RNA could target to and accumulate in tumor at least 24 hours." (PMID 38274829, 2023). "Collectively, the results indicated Iacs-eif3c-RNA exerted excellent antitumor efficacy by reducing the intracellular level of eIF3C, inhibiting cell growth and promoting apoptosis, suggesting that it has a sustainable tumor suppressor potential in vivo." (PMID 38274829, 2023). "Eukaryotic initiation factor 3C (eIF3c) has emerged as a promising therapeutic target for HNC due to its ability to regulate protein expression levels in tumor cells, but its drug development is difficult to achieve by targeting traditional protein-protein interactions." (PMID 38274829, 2023). "To determine whether nanoparticles are able to target to and accumulate in tumor site, we measured the content of gold in tumor tissue of mice, which were injected with Iacs-eif3c-RNA after 0, 4, 10 and 24 hours." (PMID 38274829, 2023). "Furthermore, it is revealed that in HNSCC xenograft mouse models constructed with cisplatin-resistant cell line, Iacs-eif3c-RNA demonstrated superior anti-tumor efficacy and remarkable biosafety compared to cisplatin." (PMID 38274829, 2023). "eIF3C is a core subunit of eIF3, which is responsible for coordinating the interaction between initiator and ribosome for translation, and its translation regulation is involved in the development and progression of many tumours." (PMID 34794452, 2021). "Lee HYand other researchers have found that the expression of EIF3C could enhance HCC cells to secrete exosomes, causing tube formation of HUVEC cells and tumor growth, eventually leading to tumor angiogenesis." (PMID 31901224, 2020). "Increased levels of eIF3C positively correlated with tumor grades." (PMID 31795417, 2019). "Other elements of EIF3 complex as well as translational machinery such as EIF3B, EIF3C, EIF4A, EEF1A, and EEF2 were already revealed as components of tumor-associated exosomes, which implicates exosomal delivery of translational machinery including EIF3A can be involved in tumor propagation." (PMID 31363116, 2019). "Levels of nine eIF3 subunits involving eIF3A, eIF3B, eIF3C, eIF3D, eIF3E, eIF3H, eIF3I, eIF3J, and eIF3M were significantly increased in cancer tissues, whereas the eIF3L expression level in tumours was independently decreased than that of normal tissues (p < 0.05)." (PMID 31885740, 2019). "In this study, we explored the roles of EIF3C upregulation in the tumor progression of HCC." (PMID 29568350, 2018). "Omics approaches to reveal other tumorigenic components such as proteins, RNAs and non-coding RNAs in EIF3C-exosomes could further dissect the EIF3C upregulation mediated tumor progression." (PMID 29568350, 2018).
tumor (continued). "Silencing of EIF3C via knockdown or interacting with schwannomin could induce cell apoptosis and suppress cell proliferation and tumor growth." (PMID 29568350, 2018). "Through photo observation and volume and weight analysis of the tumor masses, it was found that the tumor masses in the experimental group were small in size and low in weight, indicating that down-regulation of EIF3C could inhibit the formation and growth of tumor cells in mice." (PMID 36147539, 2022). "Next, we hypothesized how EIF3C regulated tumor progression." (PMID 35650605, 2022). "It was thus deduced that ZNF280A may act as a tumor driver in LUAD by influencing EIF3C expression." (PMID 33414445, 2021). "We hypothesized that EIF3C might enhance secretion of exosomes to promote tumor angiogenesis." (PMID 29568350, 2018). "Iacs-eif3c-RNA inhibited tumor growth (TGI=56.18%) with little impact on body weights, while the combined treatment showed tumor growth inhibition (TGI=42.53%) accompanying body weight decline." (PMID 38274829, 2023). "By employing this methodology, we successfully converted eIF3C siRNAs into an HNC therapeutic agent, exhibiting anti-tumor efficacy both in cellular and animal models." (PMID 38274829, 2023). "Encouragingly, Iacs-eif3c-RNA treatment substantially suppressed tumor growth (TGI=59.41%), based on the evidences on volume and H&E staining of tumor tissues." (PMID 38274829, 2023). "We also validated concordant protein expression of EIF3C and S100A11 on HCC tumor tissues by IHC assays." (PMID 29568350, 2018). "The photographic results showed that tumor was smaller after treated with no matter Iacs-eif3c-RNA alone or a combination of Iacs-eif3c-RNA with DDP." (PMID 38274829, 2023). "Conversely, the utilization of Iacs-eif3c-RNA demonstrated an enhanced therapeutic outcome in terms of inhibiting tumor growth, while not inducing any obvious toxicity symptoms." (PMID 38274829, 2023). "Both the Iacs-eif3c-RNA monotherapy and combination therapy showed evident tumor suppression, while DDP alone did not significantly reduce tumor weight." (PMID 38274829, 2023). "Moreover, both exosome and exosomal S100A11 secretion were elevated by eukaryotic translation initiation factor 3 subunit C (EIF3C) stimulation, which was up-regulated during HCC tumor development." (PMID 30897788, 2019). "Expression of EIF3C did not alter proliferation and expression of other tumor progressive genes such as HIF1A, TGFβ1 and VEGF, but reduced cell migration in HCC cells." (PMID 29568350, 2018). "Except EIF3E and EIF3F found down-regulated and conferred tumor suppressive activity in cancers, majority of EIF3 members including EIF3A, EIF3B, EIF3C, EIF3D, EIF3H, EIF3I and EIF3M were up-regulated and played important roles in tumor progression of multiple cancer types." (PMID 29568350, 2018). "Besides, nine eIF3 subunits beyond eIF3D were found aberrantly expressed in LUAD tissues and in which the expression levels of five subunits (eIF3B, eIF3C, eIF3E, eIF3H, and eIF3J) increased in LUAD patients with high tumour stage, implicating their roles in the maintenance or progression of LUAD." (PMID 31885740, 2019).